IL6 (interleukin 6)
Diseases named in the same sentence as IL6 in open-access papers (continued):
Sharing a sentence is not in itself a finding about the gene and the disease.
tumor (continued). "The production of chemokines and cytokines such as TNF-α, IL-6, and IL-1β by activated macrophages plays a critical role in diverse physiological processes, particularly in a host's innate immunity system to inhibit microbial growth, tumor cell growth, and tumor metastasis." (PMID 24574581, 2013). "Therefore, an elevated CRP might indicate tumours capable of producing significant amounts of proinflammatory cytokines, in particular interleukin-6." (PMID 23497335, 2013). "Thus it is hypothesized that sG-CSF, sM-CSF and IL-6 may indirectly assist tumor growth and progression by neutrophilia." (PMID 23599759, 2013). "We therefore determined whether IL-6 mediated IL-17-driven Stat3 activation in a tumor setting." (PMID 24453427, 2013). "Our observations suggest that HY-PDT induced apoptosis in HepG2 cells by facilitating increased IL-6 secretion and inflammation, to potentially recruit inflammatory cells, providing additional hints for the existence of alternative mechanisms of anti-tumor immunity in HCC." (PMID 23807226, 2013). "Therefore, diagnosis of G-CSF- and IL-6-producing tumor was established." (PMID 23710188, 2013). "Therefore, induction of angiogenesis may be one of the mechanisms responsible for tumor promotion by IL-6." (PMID 23637926, 2013). "We concur that tumor reduction after P2Et treatment cannot simply explain IL-6 serum reduction and hypothesize that some other immune-regulatory mechanisms are mediated by the P2Et fraction cannot be excluded, including the inhibition of suppressor macrophages." (PMID 23552194, 2013). "To test this hypothesis we measured IL6 and Ret levels in J110 tumours." (PMID 23868506, 2013). "We observed a decrease in circulating IL-6 that may have been correlated with the reduction in tumor volume and metastasis; however, it also may have been correlated with negative regulation of the inflammatory microenvironment, favoring the activation of mechanisms implied in tumor elimination." (PMID 23552194, 2013). "In addition, ex vivo incubation of TAM with exosomes from EGCG-treated 4T1 cells skewed polarized these macrophages away from the tumor-promoting M2- to a tumor-inhibiting M1-like phenotype, as evidenced by down-regulated the expression of IL-6 and TGF-β, but up-regulated TNF-α expression." (PMID 24044575, 2013). "Furthermore IL-6 may also provide tumor cells with mechanisms to escape cell death induced by stress and cytotoxic drugs, such as increased expression of several survival proteins, i.e. Bcl-2, Bcl-xL, Mcl-1, survivin, and XIAP." (PMID 23517603, 2013). "Moreover, corroborating with a decreased incidence of tumor formation, we found that within the tumor mass, which includes tumor and host cells, mRNA levels of two pro-inflammatory cytokines, IL-6 and IFN-γ, were up-regulated in tumors from B1 receptor-stimulated cells compared to controls." (PMID 23691222, 2013). "Therefore, it is possible that IL-6 produced by the tumor elicited the production of G-CSF." (PMID 22713692, 2012). "In a mouse model of Burkitt's lymphoma, Gilbert and Hemann showed that IL-6 was released in the thymus in response to doxorubicin treatment, creating a “chemoresistant niche” that promotes the survival of a minimal residual tumor burden and serves as a reservoir for eventual tumor relapse." (PMID 22778760, 2012). "However, following tumor progression, high level of IL-1β, and possibly IL-23 as well, with the reduced levels of IL-6 and TGF-β may become supporting cytokine milieu for the expansion of Th17 cells in tumor tissues." (PMID 22994684, 2012). "Also, fluorescence microscopy of tumor sections 11 dpi confirmed the expression of hyper-IL-6." (PMID 22236378, 2012). "Yet IL-17A could promote tumor growth in conjunction with IL-6-dependent activation of Stat3." (PMID 22855687, 2012).
tumor (continued). "Triggering of TLR4 by LPS induced tumor promotion by the induction of proliferation, activation of NF-κB, p65 binding to DNA, and resistance to NK cell-mediated cytotoxicity accompanied by the increased production of proinflammatory cytokines (IL-6 and IL-8), VEGF." (PMID 22583829, 2012). "Finally, the high levels of IL-6 could enhance the immune suppressive status of the tumor microenvironment by inducing B7-H4 expression on tumor associated macrophages and promote apoptosis in these cells." (PMID 21619709, 2011). "For example, targeting IL-6-stimulated RANKL production by osteoblast precursors can reduce bone loss and so improve MM-induced bone lesions, while targeting IL-6-stimulated MM cell proliferation can reduce MM tumor burden and contribute to improving MM-induced bone lesions." (PMID 22110661, 2011). "Hence the elevated level of IL6 in the tumor microenvironment, besides exerting an immune stimulatory effect, may also support tumor growth and thereby limit the benefit gained by anti-tumor immune responses." (PMID 21738796, 2011). "Thus, an important question that arose during this study was whether patients with higher serum CRP (i.e., ⩾30 mg l–1) had been given an insufficient siltuximab dose to suppress their IL-6 levels adequately to achieve a tumour response." (PMID 20808314, 2010). "For instance, in vivo, treatment of tumor-bearing animals with interleukin-12 (IL-12) shifts tumor-associated macrophages from a dominant M2 profile (elevated expression of TGFβ, IL-10, and MCP1) to a proimmunogenic/inflammatory M1 profile (elevated expression of IL-6 and TNFα)." (PMID 20508742, 2010). "The intense correlation between IL-6 expression in cancer cell and a decreased sIL-6R Ca/N ratio may partly reflect exaggerated consumption of sIL-6R by increased IL-6/sIL-6R affinity in the cancer stroma, which maintains a favourable condition for tumour growth." (PMID 20823887, 2010). "Taken together, these important findings further support the notion that IL-6, as a major component of the inflammatory niche in keloid scars, may play a critical role in the acquirement of benign tumor-like stem cell phenotypes, therefore the benign tumor growth." (PMID 19907660, 2009). "Furthermore, serum levels of IL-1β and IL-6 correlate with tumor response to anti-VEGF therapy and may be predictive clinical markers." (PMID 19888452, 2009). "Importantly, our data suggest that IR-induced up-regulation of IL6 in parental SCC61 tumour cells might be one of the initial events in the activation of the Stat1 pathway." (PMID 19437244, 2009). "Administration of Paclitaxel to patients with high percentage Type I cancer cells could have detrimental effects due to Paclitaxel-induced enhancement of NF-κB and ERK activities and cytokine production (e.g. IL-6), which promote chemoresistance and tumor progression." (PMID 19619321, 2009). "Thus, one possible additional therapeutic pathway could be an inhibition of the IL-6 stimulation of the tumour cells through therapeutic use of anti-IL-6 antibodies." (PMID 18234094, 2008). "Furthermore, IL-6 was localised to the tumour and not the liver in tumour-bearing animals, suggesting that the tumour or its associated stroma is the source of IL-6." (PMID 18059400, 2008). "To determine whether VEGFR-2 expression on pCSCs is regulated by tumor environmental cues, we examined the effects of cytokines on the expression in vitro., including Flt3 ligand (FL), GM-CSF, IL-3, IL-4, IL-6, IL-7 and IL-13." (PMID 18286204, 2008). "However, the level of IL-6 was significantly elevated in all tumour models compared with controls." (PMID 18059400, 2008). "However, tumour cures were enhanced by Hyper-IL-6 administration from 0 to 20% with 88 J cm−2 PDT (median time to growth to 400 mm3 11.5 days and 13.3 days, respectively) and from 20 to 60% with 128 J cm−2 PDT (median time to growth to 400 mm3 21.7 days and >60 days, respectively)." (PMID 17987036, 2007).
tumor (continued). "Therefore, it is unclear whether PDT surviving tumour cells are subject to regulation by IL-6 and whether this regulation could contribute to tumour control by PDT." (PMID 17987036, 2007). "However, resection of the primary tumour did not appear to be associated with significant normalisation of circulating concentrations of C-reactive protein, interleukin-6 or interleukin-10." (PMID 17003778, 2006). "This might therefore suggest that interleukin-6 is produced by the tumour cells." (PMID 15700032, 2005). "This might suggest that the tumour was responsible for the increased production of interleukin-6." (PMID 15505624, 2004). "However, tumour-specific immune interaction with T cells, macrophages or monocytes might also be responsible for elevated Il-6 levels, as these cell are known to produce this cytokine, too." (PMID 15280926, 2004). "Moreover, it may also be that interleukin-6, produced by tumour-infiltrating leucocytes, stimulates tumour cell proliferation and promotes leucocyte recruitment as part of an autocrine growth factor loop." (PMID 15505624, 2004). "Indeed, there is some evidence that IL-6 produced by such tumour cells may act as an autocrine growth factor promoting the survival and invasion of the tumour into surrounding tissue." (PMID 15570310, 2004). "No apparent differences were detected in the cellular homogeneity or viability of fibroblasts derived from tumour or proximal breast tissues that might explain the marked differences in basal and IL-6+IL-6sR-stimulated aromatase activity in these different fibroblasts." (PMID 12592380, 2003). "The colon 26 tumour grown in the liver does not lose its ability to cause cachexia, because the tumour when re-inoculated s.c. is able to cause extensive weight loss and produce IL-6 as did the original colon 26 cell line." (PMID 10070867, 1999). "In comparison, mouse fibroblasts from KPT tumors were enriched with cells highly expressing tumor-suppressing inflammatory CAF (iCAF) markers, including Has1, Ccl2, Il6, and Cxcl2 (clusters 1–3)." (PMID 41480763, 2026). "For instance, during acute SARS-CoV-2 infection, a surge of IL-6 has been recently shown to awaken dormant tumor cells and drive cancer progression, a process facilitated by suppressive CD4+ T cells within the tumor microenvironment." (PMID 41315764, 2026). "In cancer-associated fibroblasts, GPR68 senses the acidic tumor microenvironment and enhances IL-6 expression via a cAMP-PKA-CREB pathway, thereby promoting tumor cell proliferation." (PMID 41595528, 2026). "C1-GBM is characterized by an immune-infiltrated microenvironment with significant IL6 pathway activity, whereas C2-GBM is marked by tumor driver and activation of G2/M checkpoint for the cell cycle." (PMID 41614933, 2026). "Targeting oncogenic signaling pathways, Lactobacillus rhamnosus and B. pseudolongum inhibit IL-6/STAT3 pathway activity by reducing IL-6 levels or enhancing STAT3 methylation, respectively, and thus blocking tumor cell growth and angiogenesis." (PMID 40990659, 2026). "IL‐8, IL‐6, and CXCL1 are factors involved in neutrophil recruitment, and neutrophils contribute to tumour progression." (PMID 41503680, 2026). "Second, the expression of two pro-inflammatory factors, interleukin 6 (IL6) and interleukin 8 (IL8), was also investigated in the tumor site." (PMID 41596451, 2026). "AP1S1 showed enrichment for IL6-JAK-STAT3 and TNFα-NFκB signaling, as well as apoptosis and G2/M checkpoint pathways, suggesting involvement in both metabolic regulation and tumor-immune interactions." (PMID 41438582, 2026). "Accumulating evidence indicates that inflammatory mediators-including CCL2, CCL3, CCL5, CXCL1, CCL20, TNF-α, IL-6, IL-8, and TGF-β-contribute to tumor growth, metastasis, immune modulation, and therapeutic resistance." (PMID 42245673, 2026).
tumor (continued). "In ovarian cancer, embryonic TAMs expressing CD163 and T‐cell immunoglobulin and mucin‐domain containing molecule 4 (Tim4) produce high levels of IL‐6 and erythropoietin, activating STAT3 to promote tumor progression and invasion." (PMID 41426206, 2026). "Tumor recognition by CAR T cells induces IFN‐γ and other cytokines, activating monocytes/macrophages → this amplifies inflammation through IL‐6, IL‐1, IL‐10, and TNF." (PMID 41207679, 2026). "In our experiments, LyECs exhibited significant increases in IL-6 secretion and STAT3 activation, both of which are known to promote lymphangiogenesis and tumor progression." (PMID 41583514, 2026). "In the TCGA CCA cohort, high expression of IL6, TNF, AKT1, and STAT3 and low expression of PPARG correlated with advanced tumor stage and poorer overall survival (e.g., IL6: ρ = 0.42, p = 0.01)." (PMID 41899527, 2026). "In tumor-bearing mice, antitumor efficacy, serum cytokines (TNF-α, IFN-γ, IL-6, IL-2, IL-10), and hematological indices were evaluated." (PMID 41965546, 2026). "Inflammatory CAFs (iCAFs) secrete pro-inflammatory cytokines, such as interleukin-6 (IL-6) and C-X-C motif chemokine ligand 12 (CXCL12), which influence immune cell recruitment and promote tumor-promoting inflammation." (PMID 41590379, 2026). "Double-ICI combinations and multi-modality regimens remain limited, with ctDNA, bTMB, IL-6 and AFP, CTC, ctDNA emerging as predictors, underscoring the broad applicability of tumor-related markers." (PMID 41535994, 2026). "In 4T1 tumor‐bearing mice, PCN significantly elevated serum levels of IL‐6, IL‐12, and IL‐1β, comparable to LPS‐induced fever, while promoting dendritic cell maturation and robust CD8+ T cell infiltration." (PMID 41298282, 2026). "Formalin-fixed paraffin-embedded samples from tumor, peritumoral, and normal renal tissues were examined using confocal immunofluorescence microscopy to assess PTX3, IL-6, p21, and p16 expression." (PMID 41681886, 2026). "These MSC-derived CAFs contribute to extracellular matrix remodeling, enhance tumor cell invasion, and secrete a range of pro-tumorigenic factors, including TGF-β, IL-6, and CXCL12." (PMID 41595527, 2026). "IL-6 neutralization or HERC1 inhibition sensitized organoids to 5-fluorouracil and cisplatin, and combined HERC1 knockdown with 5-FU markedly reduced tumor growth and increased apoptosis." (PMID 41965446, 2026). "After their initial conversion, CAFs expansion and sustained activation are mainly driven by tumor-secreted factors such as TGF-β, PDGF, and IL-6 41-44." (PMID 41355964, 2026). "Among these, interleukins such as IL-6, IL-8, and IL-10, along with chemokine axes including CXCL12-CXCR4 and CCL21-CCR7, are critical drivers of tumor progression and resistance to immunotherapy." (PMID 41884817, 2026). "The clinical picture was consistent with a tumor-induced CRS, evidenced by markedly elevated interleukin-6 (IL-6) and C-reactive protein (CRP)." (PMID 42164115, 2026). "For example, IL-6 and TNF-α have been shown to protect tumor cells from the cytotoxic effects of chemotherapy and radiation by activating survival pathways such as AKT and MAPK." (PMID 41497141, 2026). "M2 TAMs also secrete IL-6 and IL-8, promoting epithelial–mesenchymal transition (EMT) and tumor cell motility." (PMID 41597210, 2026). "It stimulates the production of pro-inflammatory cytokines, including IFN-α, IL-6, and TNF-α, and activation of TLR7/8 promotes a Th1-mediated anti-tumor response dependent on IFN-γ." (PMID 41601666, 2026). "IL6/IL6R/STAT3 and HIF1α/ZEB1 pathways induce epithelial to mesenchymal transition (EMT) and CAFs secrete EGF, FGF and HGF for tumour growth." (PMID 41476776, 2026). "Suppression of tumor-suppressive signaling (WNT/β-catenin and TGF-β regulation) and dysregulation of immune pathways (IL-6, IFN-α/β, and Th17 signaling) were observed, collectively favoring a microenvironment conducive to malignant transformation." (PMID 41399370, 2026).
tumor (continued). "The resulting humanized antibodies, huE17 and huNA7, exhibited target specificity and effectively inhibited IL-6 induced STAT3 activation and tumour promoting phenotypes in vitro." (PMID 42316398, 2026). "To investigate the ameliorative effects of ginsenoside Re on UVB-induced inflammation and oxidative stress in skin photodamage, we measured the levels of CAT, SOD, GSH-Px, MDA, T-AOC, IL-6, IL-8, and TNF-α in rat skin tissues." (PMID 41596360, 2026). "IL-37 suppresses many pro-inflammatory pathways, including NF-κB, MAPK, and the cytokines IL-1β, IL-6, and TNF, thereby inhibiting tumor growth." (PMID 41596472, 2026). "In detail, STAT3, activated by cytokines such as IL‐6 and IL‐10 alongside growth factors including epidermal and fibroblast, mediates JAK/STAT signaling, a pathway critical for tumor progression and chemoresistance." (PMID 41509196, 2026). "This environment promotes immunosuppressive populations—including M2‐polarised TAMs, MDSCs and Tregs—which secrete cytokines such as IL‐6, IL‐10 and TGF‐β to drive tumour progression and suppress effector CD8+ T cells, NK cells and DCs." (PMID 41486497, 2026). "MCs express high levels of c-kit (involved in development, survival, and migration) and its ligand SCF, which enhances tumor growth by stimulating cytokines such as VEGF, TNF, IL-6, and IL-1." (PMID 41596472, 2026). "Elevated IL-6 levels in the bone microenvironment further potentiate STAT3 activation, contributing to tumor survival and dormancy." (PMID 41596432, 2026). "In contrast, MG3, MG4, and monocyte subsets 1 and 2—which were less concentrated within tumor cores—exhibited significantly weaker engagement with pro-tumor or immunosuppressive pathways, including MIF, TNF, IL-4, IL-6, OSM, galectin, and TGF-β." (PMID 41503214, 2026). "EATL is characterized by strong inflammatory activity, with enriched gene sets like interferon response and IL-6/JAK/STAT3 signaling and overexpressed inflammation-related genes (e.g., PD-L1, CXCL13), suggesting STAT3-driven tumor-promoting inflammation." (PMID 41057685, 2026). "For example, IL-6 from both M1 and M2 macrophages activates the JAK-STAT3 pathway, supporting tumor-cell survival and proliferation." (PMID 41438574, 2026). "The IL-6 and IL-23 receptors signal through signal transducer and activator of transcription 3 (STAT3) in the tumor microenvironment." (PMID 41749853, 2026). "These cells contribute to matrix remodeling, angiogenesis, and extracellular matrix reconstruction by secreting IL‐6, IL‐10, TGF‐β, and matrix metalloproteinases, thereby supporting tumor cell migration, peritoneal implantation, and metastasis." (PMID 41426206, 2026). "Serum levels of IL-6 are higher in patients with untreated metastatic or castration-resistant prostate cancer (CRPC) and are inversely related to tumor survival and chemotherapy response." (PMID 41596531, 2026). "IFIT2 knockdown significantly increased IL-6 mRNA and secretion levels in OSCC cells, indicating IFIT2's potential regulatory role in inflammation within the tumor microenvironment." (PMID 41619016, 2026). "These invading cells also release pro-inflammatory substances like interleukin-6 (IL-6) and tumor necrosis factor-alpha (TNF-α), which in turn promote tumor growth, metastasis, and therapy resistance." (PMID 41614944, 2026). "Functionally, they promote tumor progression by stimulating proliferation via FGF, IL-6, and CXCL12." (PMID 41601669, 2026). "Tumor-derived factors such as transforming growth factor-beta (TGF-β), interleukin-6 (IL-6), and vascular endothelial growth factor (VEGF) favor the N2 phenotype, tipping the balance toward a pro-tumorigenic state." (PMID 41497164, 2026). "For example, one can envision combining optogenetic stimulation of the vagus nerve or LC—aimed at reducing systemic immunosuppression by lowering IL‐6 and TNF—with checkpoint inhibitors or tumor vaccines to convert “cold” tumors into “hot” ones." (PMID 41583906, 2026).